PLIN5 (perilipin 5)
Diseases named in the same sentence as PLIN5 in open-access papers (continued):
Sharing a sentence is not in itself a finding about the gene and the disease.
atherosclerosis (5 papers, 2019 to 2025). A disease characterized by the build-up of fatty material and calcium deposition in the arterial wall resulting in partial or complete occlusion of the arterial lumen. "Plin5 deficiency leads to accelerated atherosclerosis progression and oxidative stress in ApoE−/− mice." (PMID 38397807, 2024). "Perilipin 5 (Plin5), a regulator of lipid metabolism, is also confirmed to be involved in vascular disorders, such as microvascular endothelial dysfunction and atherosclerosis." (PMID 35470759, 2022). "Plin5 knockout exacerbates severe atherosclerosis in apoe−/− mice via promoting inflammation, lipid accumulation, and oxidative stress." (PMID 35470759, 2022). "In addition, Plin5 was also demonstrated to be involved in vascular disorders, such as microvascular endothelial dysfunction and atherosclerosis." (PMID 39859272, 2025). "Additional studies have suggested a role for Plin5 in atherosclerosis and oxidative stress." (PMID 38397807, 2024). "Plin5 is an important regulator of oxidative stress, which is significantly involved in atherosclerosis development, and its knockdown in animal models enhanced inflammation, apoptosis, oxidative stress, and lipid accumulation, thus promoting atherosclerosis progression." (PMID 39859272, 2025). "PLIN5 is a promising therapeutic target for NAFLD and atherosclerosis, and possibly for some other metabolic diseases." (PMID 34203309, 2021).
cardiomyopathy (5 papers, 2020 to 2025). A disease of the heart muscle or myocardium proper. "It is conceivable that low cardiac lipolysis in Plin5-Tg mice and reduced PPARα-activated gene expression cause a similar adaptation and lower cardiac FA uptake, thereby protecting mice from the development of lethal cardiomyopathy." (PMID 37150323, 2023). "Both Plin5-null and overexpression models clearly showed that Plin5 is essential for normal cardiac functions and metabolism, but above all, the higher expression of Plin5 is central to cardiomyopathy development." (PMID 39859272, 2025). "Therefore, we can speculate that Plin5 may play a bidirectional role in lipid metabolism, while the deficiency of Plin5 reduces the synthesis of TG and LD in cells, and even promotes the appearance of cardiomyopathy related to lipid metabolism in the heart." (PMID 35509833, 2022). "In summary, the studies on various gene models of Plin5 indicate that Plin5 is required for normal cardiac metabolism and function, but too much Plin5 may lead to cardiomyopathy." (PMID 35401929, 2022).
heart failure (5 papers, 2022 to 2026). Inability of the heart to pump blood at an adequate rate to meet tissue metabolic requirements. "The activation of the Nrf2 antioxidant pathway can prevent the progression of Plin5-overexpressing hearts to heart failure." (PMID 40166465, 2025). "We show that Plin5-Tg mice are still protected from the development of heart failure albeit the cardiac function declines with age likely due to prolonged exposure to metabolic stress." (PMID 37150323, 2023). "Accordingly, low cardiac lipolysis in Plin5-Tg mice divergently impacts heart function and whole body energy homeostasis compared to GLUT1 transgenic mice and further implicates that the metabolic changes in Plin5-Tg mice are not the consequence of heart failure." (PMID 37150323, 2023).
type 2 diabetes (5 papers, 2016 to 2024). "PLIN5 gene expression and protein content upon an endurance training intervention increases in obese participants and individuals with type 2 diabetes." (PMID 32529413, 2020). "Interestingly, increased abundances of Romboutsia have been detected Plin5-deficient animals in MAFLD-HCC model, despite their previous association with the severity of MAFLD and type 2 diabetes." (PMID 39469452, 2024). "Interestingly, the number of PLIN5-coated lipid droplets in endurance-trained athletes is higher than in individuals type 2 diabetes." (PMID 32529413, 2020). "It should be noted, though, that trained individuals possess higher PLIN5 levels, have more PLIN5-coated lipid droplets and may, thus, have more lipid droplet–mitochondrial interaction sites than individuals with type 2 diabetes." (PMID 32529413, 2020). "Increased PLIN5 protein content upon endurance training indicates that IMCL use during exercise is facilitated and that lipolysis rates of lipid droplets are better matched to mitochondrial fatty acid oxidation rates in individuals with type 2 diabetes vs baseline." (PMID 32529413, 2020).
myocardial infarction (4 papers, 2017 to 2025). Gross necrosis of the myocardium, as a result of interruption of the blood supply to the area, as in coronary thrombosis. "In a study of Plin5 gene in patients with clinical myocardial infarction, Plin5 gene mutation is related to cardiac dysfunction after myocardial infarction." (PMID 35401929, 2022). "Our results indicated that Plin5 deficiency exacerbated the myocardial infarct area, aggravated left ventricular systolic dysfunction, reduced lipid storage, and elevated free fatty acids." (PMID 28218306, 2017). "All of these results suggested that Plin5 inhibits ROS production, reduces myocardial infarct size, and protects the I/R myocardium." (PMID 28218306, 2017). "The results indicated that the myocardial infarct size of the Plin5-null mice was significantly increased compared to that of the wide-type mice with I/R surgery (46.29 ± 2.397% vs. 28.33 ± 2.516%; P < 0.01)." (PMID 28218306, 2017). "This study explored the impact of PLIN5 on ferroptosis in H9c2 cells and a rat model of myocardial infarction (MI)." (PMID 40665985, 2025). "Thus, the Plin5−/− mice hearts have a diminished contact between mitochondria and lipid droplets combined with a reduced storage pool of lipids, resulting in a reduced heart function after myocardial infarction." (PMID 31061399, 2019).
diabetic cardiomyopathy (3 papers, 2022 to 2025). Diabetic cardiomyopathy is a disorder of the heart muscle in people with diabetes. "By modulating lipid droplet storage functions and anchoring droplets to mitochondria, PLIN5 alleviates diabetic cardiomyopathy through PGC1α-PPARα axis activation—a key regulatory pathway in energy metabolism." (PMID 40665985, 2025). "Here, the purpose of this review is to summarize the present understanding of the bidirectional regulation role of Plin5 in oxidative tissues and to reveal its potential role in diabetic cardiomyopathy protection." (PMID 35401929, 2022). "Undoubtedly, more work is needed to understand the role of Plin5 in cardiomyocyte biology before it can be considered as a valuable therapeutic target for translational studies of diabetic cardiomyopathy." (PMID 35401929, 2022). "Overall, Plin5 serves as a bidirectional switch in oxidative tissues, and this knowledge could lead to new avenues of therapy and prevention of diabetic cardiomyopathy." (PMID 35401929, 2022). "As a member of Plins superfamily, perilipin 5 (Plin5) coats LDs in cardiomyocytes, which is significantly related to reactive oxygen species (ROS) production originated from mitochondria in the heart, consequently determining the progression of diabetic cardiomyopathy." (PMID 35401929, 2022). "Therefore, Plin5 may serve as a bidirectional regulator for lipid turn over by phosphorylation modification and content variation in cardiomyocytes and act as a potential molecular target for the treatment of dyslipidemia in diabetic cardiomyopathy." (PMID 35401929, 2022).
liver disease (3 papers, 2024 to 2025). "In conclusion, the study underscores the importance of Plin5 as a key regulator of gut microbiota in the context of liver disease and highlights the potential of microbiome modulation as a therapeutic avenue." (PMID 39469452, 2024). "The broader implications of these findings suggest that targeting PLIN5 could serve as a potential therapeutic strategy to modulate gut microbiota and mitigate liver disease progression." (PMID 39469452, 2024). "This suggests that developing pharmacological inhibitors or knockout therapies targeting Plin5 could help prevent the advancement of liver disease." (PMID 39469452, 2024). "Without direct measurement of metabolites, such as short-chain fatty acids or bile acids, the exact mechanisms by which Plin5 influences liver disease through gut microbiota remain speculative." (PMID 39469452, 2024).
type 1 diabetes (3 papers, 2020 to 2023). "Existing research suggests that Plin5 can prevent type 1 diabetes-induced heart malfunction and protect the heart from ischaemia‒reperfusion injury by inhibiting the lipolysis of LDs." (PMID 37667357, 2023). "Diabetic Plin5-ablation mice are resistant to type 1 diabetes-induced heart malfunction due to the suppression of diacylglycerol/ceramide-PKC pathway and excessive ROS generated by NADPH oxidase." (PMID 35401929, 2022). "The authors have found that diabetic Plin5−/− mice are resistant to type 1 diabetes-induced heart malfunction due to the suppression of the diacylglycerol/ceramide-PKC pathway and of excessive ROS generation by nicotinamide adenine dinucleotide phosphate (NADPH) oxidase." (PMID 35401929, 2022). "In a study involving type I diabetes, the results were just the opposite: compared with WT, Plin5−/− mice did not exhibit excessive ROS generation or cardiac dysfunction but had an improvement in heart function although LDs decomposition increased." (PMID 35401929, 2022).
breast carcinoma (2 papers, 2021 to 2022). "For example, the Kaplan–Meier survival curves for patients with breast cancer showed that high expression of PLIN5 mRNA was significantly correlated with a better SP." (PMID 34499029, 2021). "Accordingly, our data showed that radioresistant breast cancer cells were characterized by a downregulation of PLIN5." (PMID 34499029, 2021).
colon cancer (2 papers, 2022 to 2023). "miR-4284 acts as an anti-tumor miRNA in colon cancer, which reduces perilipin 5 and inhibits epithelial-to-mesenchymal transition, leading to inhibited colon cancer tumorigenesis." (PMID 37568704, 2023).
diabetes mellitus (2 papers, 2023). A metabolic disorder characterized by abnormally high blood sugar levels due to diminished production of insulin or insulin resistance/desensitization. "In our study in AS patients, myostatin emerged as a significant predictor of ventricular fibrosis, independent of age, gender, BMI, diabetes mellitus, statin therapy, apoptosis, PLIN5, and ceramides, explaining approximately 40% of the variance." (PMID 37958492, 2023).
fibrosis (2 papers, 2023 to 2026). the formation of excess fibrous connective tissue in an organ or tissue in a reparative or reactive process. "Consistent with improved cardiac function, restoring PLIN5 in Kif13b−/− mice attenuated myocardial fibrosis and lipid accumulation and more profoundly, reduced oxidative stress relative to that in Kif13b−/− controls." (PMID 41531892, 2026). "We interestingly observed a significant positive association between interstitial fibrosis and the number of apoptotic cardiomyocytes (r = 0.454; p = 0.007), as well as between fibrosis and the area covered by PLIN5 (r = 0.389; p = 0.019)." (PMID 37958492, 2023). "After BMI adjustment, we found a positive association between fibrosis and apoptotic cardiomyocytes, as well as fibrosis and the area covered by PLIN5." (PMID 37958492, 2023). "After adjustment for age and BMI, we found a positive relationship between PLIN5 and E/A and a negative correlation between septal S’, global longitudinal strain (GLS), and fibrosis." (PMID 37958492, 2023).
Hepatic fibrosis (2 papers, 2023 to 2024). The presence of excessive fibrous connective tissue in the liver. "Plin5 knockout (KO) worsened NASH-associated characteristics in mice given a high-fat/high-cholesterol (HFHC) diet, such as lipid accumulation, inflammation and hepatic fibrosis." (PMID 37349836, 2023).
ischemia (2 papers, 2021 to 2022). A hypoperfusion of the BLOOD through an organ or tissue caused by a PATHOLOGIC CONSTRICTION or obstruction of its BLOOD VESSELS, or an absence of BLOOD CIRCULATION. "Moreover, activation of perilipin 5 has been shown to protect hearts against oxidative stress and ischemia." (PMID 35047577, 2021).
left ventricular hypertrophy (2 papers, 2017 to 2019). Enlargement of the LEFT VENTRICLE of the heart. "Interestingly, Plin5 overexpression in the heart caused severe cardiac steatosis and left ventricular hypertrophy." (PMID 31772713, 2019).
leiomyosarcoma (2 papers, 2020 to 2021). An uncommon, aggressive malignant smooth muscle neoplasm, usually occurring in post-menopausal women. "PLIN2, PLIN3 and PLIN5 were widely expressed in liposarcomas, rhabdomyosarcomas, leiomyosarcomas, dermatofibrosarcoma protuberans, undifferentiated sarcomas, fibrosarcomas, Ewing's sarcomas and epithelioid sarcomas." (PMID 32368290, 2020). "PLIN5 expressed in all epithelioid sarcomas (8/8), in more than half of undifferentiated sarcomas (27/34), fibrosarcomas (15/18), Ewing's sarcomas (13/17), rhabdomyosarcomas (14/22) and leiomyosarcomas (24/42), and in less than half of dermatofibrosarcoma protuberans (17/38)." (PMID 32368290, 2020). "Regarding HCC, recent reports have shown increased expression of PLIN5 in HCC, ccRCC, and lipo-, rhabdo- and leiomyosarcoma by immunohistochemical analysis." (PMID 34067931, 2021).
liposarcoma (2 papers, 2020 to 2023). A usually painless malignant tumor that arises from adipose tissue. "The expression levels of PLIN1 (P<0.001), PLIN2 (P<0.05), PLIN3 (P<0.05), and PLIN5 (P<0.001) were closely related to the histological type of liposarcoma." (PMID 32368290, 2020). "The presence of PLIN5 has also been reported in liposarcomas and rhabdomyosarcomas." (PMID 37189627, 2023). "PLIN5 expression increased with adipocytic differentiation of liposarcoma." (PMID 32368290, 2020). "The expression rates of PLIN1 (P<0.001), PLIN2 (P=0.034), and PLIN4 (P<0.001) were significantly different in subtypes of liposarcoma, while the expression rates of PLIN3 (P=0.25) and PLIN5 (P=0.051) were not significantly different." (PMID 32368290, 2020).
liver cancer (2 papers, 2020 to 2023). An epithelial or non-epithelial malignant neoplasm that arises from the liver. "Nevertheless, since we proved that IL-6-mediated upregulation of PLIN5 at the protein level is not limited to a specific liver cell line, we concluded that this is a newly discovered mechanism of PLIN5 regulation in hepatic cancer cells." (PMID 37108378, 2023). "We show for the first time that PLIN5 expression in liver cancer cells lines is regulated by cytokines." (PMID 37108378, 2023). "In particular, we investigated the impact of IL-1β, IL-6, TNF-α, and TGF-β on PLIN5 expression in different human liver cancer cell lines." (PMID 37108378, 2023). "In summary, we found a novel mechanism of PLIN5 regulation in human liver cancer cells." (PMID 37108378, 2023). "Therefore, we initially investigated the effect of cytokines contributing to the HCC microenvironment on PLIN5 expression in the human liver cancer cell line Hep3B." (PMID 37108378, 2023). "As no previous research has investigated the potential influence of cytokines on PLIN5 expression in NAFLD progression and HCC microenvironment, we studied the effects of several cytokines on PLIN5 expression in human liver cancer cell lines." (PMID 37108378, 2023). "At the cellular level, YBX3 and CH25H were highly expressed in liver cancer cell lines, and ABCA6, PLIN5, AMACR, AKR1D1, CYP27A1, CYP46A1 were highly expressed in liver cancer cell lines in CCLE." (PMID 32627826, 2020). "However, it has not yet been reported that cytokines are able to regulate PLIN5 expression in liver cancer cell lines." (PMID 37108378, 2023).
bone metastasis (1 paper, 2020). Transfer of a neoplasm from its primary site to bones. "More importantly, among the OS-SEs, we identified two bone metastasis-related ASEs (ABCA6-43162-AT and PLIN5-46808-AT) co-expressing with SF YBX3 and pathway of primary bile acid biosynthesis." (PMID 32627826, 2020).
coronary heart disease (1 paper, 2019). "Plin5 can be used as a new indicator to predict the occurrence and development of coronary heart disease." (PMID 31772713, 2019).
epithelioid sarcoma (1 paper, 2020). An aggressive malignant neoplasm of uncertain differentiation, characterized by the presence of epithelioid cells forming nodular patterns. "Kruskal-Wallis test analysis found that the expressions of PLIN2 (P<0.001), PLIN3 (P<0.001) and PLIN5 (P = 0.013) had a significant difference in various non-lipomatous sarcomas, except for epithelioid sarcomas." (PMID 32368290, 2020). "However, due to the small sample size of epithelioid sarcomas, we analyzed the expression of perilipins in the remaining six sarcomas and found that PLIN2, PLIN3 and PLIN5 showed different and rich expressions in non-lipomatous sarcomas, especially high-grade sarcoma." (PMID 32368290, 2020).
glioma (1 paper, 2023). A benign or malignant brain and spinal cord tumor that arises from glial cells (astrocytes, oligodendrocytes, ependymal cells). "Our study demonstrated that PLIN5 had low expression in glioma patients and was associated with better survival." (PMID 37189627, 2023).
Hypercholesterolemia (1 paper, 2023). An increased concentration of cholesterol in the blood. "We also observed that Plin5 KO increased TG and TC level in the liver, indicating aggravation of hypertriglyceridemia and hypercholesterolemia by Plin5 deficiency in an HFHC diet-induced NASH mouse model." (PMID 37349836, 2023).
hypertrophic cardiomyopathy (1 paper, 2022). A condition in which the myocardium is hypertrophied without an obvious cause. "PLIN5 serves as a metabolic modulator of cardiac LDs and is highly expressed in hypertrophic cardiomyopathy." (PMID 36295596, 2022).
irritable bowel syndrome (1 paper, 2024). Irritable bowel syndrome (IBS) is a chronic functional condition of the lower gastrointestinal (GI) tract characterized by abdominal pain or discomfort and disordered bowel habit (diarrhea, constipation, or fluctuation between the two). "Furthermore, Alloprevotella, which has been found to be significantly enriched in fecal samples of patients with irritable bowel syndrome was reduced in Plin5-/- mice." (PMID 39469452, 2024).
ischemic cardiomyopathy (1 paper, 2025). Ischemic cardiomyopathy is a cardiomyopathy in which a weakness in the muscle of the heart due to inadequate oxygen delivery to the myocardium with coronary artery disease being the most common cause. "Plin5 deficiency impairs mitochondrial proliferation in ischemic cardiomyopathy, leading to severe mitochondrial injury." (PMID 40166465, 2025). "In ischemic cardiomyopathy, the myocardial Z-line and M-line sarcomeres are relatively clear, whereas Plin5-null mice exhibit severe mitochondrial deformation, increased oedema, reduced matrix density, and blurred mitochondrial cristae, indicating significant mitochondrial injury." (PMID 40166465, 2025). "A reduction in PI3K/Akt phosphorylation levels in the absence of Plin5 exacerbates ischemic cardiomyopathy." (PMID 40166465, 2025).
myocardial diseases (1 paper, 2023). "However, the roles of Plin5 in myocardial diseases need to be intensively investigated." (PMID 37667357, 2023).
oral cancer (1 paper, 2022). "The expression levels of FABP3, PPARG, PLIN5, ACACB, and PDK4 in oral cancer samples were significantly lower than those in adjacent normal samples (all p < 0.05) and then were included in the prognosis analysis." (PMID 36478991, 2022).
overnutrition (1 paper, 2019). An imbalanced nutritional status resulting from excessive intake of nutrients. "As expected, overexpression of PLIN5 inhibited overnutrition-induced ER stress in INS-1 cells indicated by blocking ER stress markers, which is similar to previous data from liver." (PMID 31384284, 2019).